KL (klotho)
Diseases named in the same sentence as KL in open-access papers (continued):
Sharing a sentence is not in itself a finding about the gene and the disease.
cancer (104 papers, 2010 to 2026). A tumor composed of atypical neoplastic, often pleomorphic cells that invade other tissues. "Existing research indicates that pro-inflammatory cytokines can suppress Klotho gene expression by activating NF-κB, a mechanism particularly evident in high-inflammatory states associated with cancer." (PMID 40519908, 2025). "For cancer mortality, the 3rd quintile of serum Klotho showed a trend of lower cancer mortality risk in Model 2 (HR 0.63, 95% CI: 0.37–1.08, P = .09)." (PMID 40696614, 2025). "This prospective cohort study revealed U-shaped associations between serum Klotho level and all-cause and cancer mortalities among US cancer adults." (PMID 40696614, 2025). "The current study found a U-shaped association between serum Klotho and cancer mortality, with serum Klotho below the inflection point demonstrating an inverse association and Klotho above the inflection point demonstrating a positive association." (PMID 40696614, 2025). "Multivariable threshold effect analysis for Klotho with all-cause and cancer mortality in cancer participants." (PMID 40696614, 2025). "Multivariable Cox regression for the associations between Klotho quintiles and mortalities in cancer participants." (PMID 40696614, 2025). "Given that prior studies have linked low levels of the klotho protein to an increased risk of cancer." (PMID 40119098, 2025). "Effect modification of age was apparent (P interaction .007); Klotho was associated positively with cancer mortality risk among participants aged under 60 (1.50, 1.09–2.05)." (PMID 40696614, 2025). "The overexpression of KL selectively targets cancer cells for apoptosis, while its reduction is linked with a poor prognosis." (PMID 40004457, 2025). "Effect modification by age was significant (P interaction = .007) for the association between Klotho and cancer mortality risk." (PMID 40696614, 2025). "The effect modification of other strata variables on the association between serum Klotho and all-cause and cancer mortality was insignificant." (PMID 40696614, 2025). "Utilizing a prospective nationally representative sample, we provided preliminary evidence on the association between serum Klotho and all-cause and cancer mortality risks in cancer individuals." (PMID 40696614, 2025). "We examined the association between serum Klotho and the risks of all-cause and cancer mortalities among 1602 cancer adults from the National Health and Nutrition Examination Survey (NHANES) (2007–2016) using multivariate Cox proportional hazard models." (PMID 40696614, 2025). "Threshold effect analyses computed inflection points of serum Klotho at 765.5 pg/mL for all-cause mortality and at 767.6 pg/mL for cancer mortality." (PMID 40696614, 2025). "Klotho was associated positively with cancer mortality risk among participants aged under 60 (1.50, 1.09–2.05)." (PMID 40696614, 2025). "In this study, the Klotho protein and various key proteins associated with cancer-, apoptosis-related, and Wnt/β-catenin pathways were quantitively identified." (PMID 38267588, 2024). "The association of serum Klotho with cancer and mortality was analyzed by weighted Logistic regression, weighted Cox regression and competitive risk model, respectively." (PMID 35841322, 2023). "As a continuous variable, the effect of serum Klotho on all the cancers covered in this study showed similar results (all p < 0.02), with each unit increase in serum Klotho (1 ug/g creatinine) associated with a 0.9%–2.2% reduction in the risk of cancers." (PMID 35841322, 2023). "The present review organized data from scientific articles published between 2012 and 2022 regarding the roles of Klotho proteins in cancer and their potential use as diagnostic and prognostic tools." (PMID 37958253, 2023). "More and more comprehensive information was needed to analyze the association between serum Klotho and cancer." (PMID 35841322, 2023).
cancer (continued). "But the research on Klotho and cancer is mainly based on animal experiments and small‐scale clinical research, thus we explored the association between serum Klotho and cancer and cancer mortality based on the National Health and Nutrition Survey (NHANES)." (PMID 35841322, 2023). "Subsequent human studies also found similar dysfunction with Klotho deficiency, particularly in cancer, cardiovascular and kidney." (PMID 35841322, 2023). "But the association between the Klotho and hormones in cancer has not been elucidated, and there is debate about the extent to which hormones mediate the value of Klotho's association with hormone‐related cancers." (PMID 35841322, 2023). "This was the first time that we analyzed the association between serum Klotho and cancer in a large‐scale population study of a nationally representative sample." (PMID 35841322, 2023). "Although the membrane-bound Klotho protein was first associated with neurodegenerative diseases, it has been linked to various other age-related disease processes, including cancer biology and cardiovascular, renal, and skin diseases." (PMID 37425590, 2023). "Our research has also increased the understanding of MDM2’s cancer promoting function, detailing how it can cause its related cell dysfunction by degrading KL." (PMID 35468874, 2022). "AKT signaling pathway is associated with proliferation/survival of various cancer cells, and Klotho overexpression has been shown to decrease activation of prosurvival phospho(p)-AKT." (PMID 36220392, 2022). "An increased Klotho promoter methylation level has already been described in several malignant neoplasms, and epigenetic silencing of Klotho expression was associated with poor prognosis." (PMID 36413367, 2022). "In recent years, Klotho has been linked to glycolysis inhibition and anti-cancer activity, which deserves more research due to its effect on Cr uptake." (PMID 34444681, 2021). "Hypermethylation of the KLOTHO promoter has been shown to be associated with progression of various forms of cancer and to correlate with kidney fibrosis in both humans and experimental fibrosis mouse models." (PMID 30158531, 2018). "Novel therapeutic strategies focused on klotho, progerin and mTOR signalling have the potential to both enhance longevity and repress cancer associated with old age." (PMID 25388238, 2015). "At the same time, differences in Klotho variant expression can influence longevity, resulting in associations between age, cancer risk and lifespan." (PMID 25388238, 2015). "Notably, our study provided preliminary evidence of such a U-shaped relationship between Klotho and all-cause mortality specifically among cancer survivors." (PMID 40696614, 2025). "The association of the serum Klotho level with cancer and mortality was analyzed." (PMID 39796185, 2025). "Serum Klotho below these thresholds demonstrated an inverse association with all-cause mortality risk and cancer mortality risk; serum Klotho above these thresholds displayed a trend of positive association with the risk of cancer mortality." (PMID 40696614, 2025). "Considering the diversity of cancer types included in our cohort and the possible heterogeneity in the association between Klotho and mortality across different cancer types, further validation in prospective studies focusing on specific cancer populations is warranted." (PMID 40696614, 2025). "Our findings suggest that maintaining an ideal Klotho level in cancer patients may be associated with reduced mortality risks." (PMID 40696614, 2025). "Klotho below these thresholds was inversely associated with all-cause mortality (Hazard ratio, HR, 95% confidence interval, CI) (0.72, 0.53–0.98) and cancer mortality (0.61, 0.39–0.96); Klotho above the threshold showed a trend of positive associated with cancer mortality (1.22, 0.99–1.50)." (PMID 40696614, 2025).
cancer (continued). "While KL is mainly known for its involvement in cognitive functions in aging, this factor is implicated in a series of other cellular processes, including insulin regulation and cell growth in cancer." (PMID 40006994, 2025). "Against this background, we prospectively evaluated whether serum Klotho level is associated with all-cause and cancer mortality risks among cancer adults from the National Health and Nutrition Examination Survey (NHANES) 2007 to 2016." (PMID 40696614, 2025). "A critical need is to identify molecular networks induced by the KL gene and its upstream regulators, which might help elucidate the mechanisms underlying the suppression of cancer malignancies." (PMID 38267588, 2024). "Klotho protein possesses various activities, including inhibition of multiple signaling pathways, reducing oxidative stress and suppressing inflammation, and these activities are associated with cancer." (PMID 37488085, 2023). "However, an association was found between Klotho gene polymorphisms and urolithiasis, cardiovascular disease (G-395A/rs1207568), cancer, and longevity (F352V/rs9536314)." (PMID 37894946, 2023). "The main reason was that we overcame some defects: Firstly, since Klotho was mainly produced in the kidney, its function would directly interfere with the content of Klotho, which may affect the association between Klotho and cancer to some extent." (PMID 35841322, 2023). "Therefore, we will use serum Klotho levels from the US NHANES database to analyze its association with the risk of cancer, all‐cause mortality, and cancer‐specific mortality, as well as sex steroid hormones." (PMID 35841322, 2023). "A recent analysis of data from the U.S. National Health and Nutrition Survey (NHANES) found that cancer was inversely associated with serum levels of klotho, a transmembrane protein produced in kidneys and the brain that functions as a cofactor with FGF23 to downregulate serum Pi." (PMID 36557322, 2022). "Considering the specific up‐regulation of Nanog in KL tumors, these observations suggest that Nanog might serve as an important factor for maintaining cancer stemness triggered by LKB1 deficiency." (PMID 33439550, 2021). "In the realm of cancer, more studies have been performed on tissue Klotho expression and illustrated its inverse association with cancer development and worsening prognoses; publications on the association between serum Klotho levels and cancer-specific mortality risk are rare." (PMID 40696614, 2025). "Among nearby DEGs of differential chromatin accessibility, only the SLC2A11 and klotho (KL) genes were shown to be possibly involved in regulating mammalian ovarian activities while others have been largely implicated in regulating cancer cell proliferation and apoptosis." (PMID 32309280, 2020). "Thus, the diagnostic role of secreted Klotho in human cancer remains controversial." (PMID 28153033, 2017). "In addition, since Klotho gene variants are associated with differential survival in three human populations, it is possible that these gene variations exert their effect on lifespan in part by affecting cancer risk." (PMID 25388238, 2015). "CONCLUSIONS: Frequent cannabis use is associated with reduced serum Klotho concentrations, a finding that may relate to biological aging-related mechanisms—particularly in metabolically healthier subgroups and individuals with prolonged sedentary behavior or cancer." (PMID 41495871, 2026). "Subgroup analyses revealed amplified Klotho reductions in frequent users with prolonged sedentary activity (> 240 min/day), higher vitamin D (serum 25(OH)D ≥ 72.5 nmol/L), and cancer (P-interaction < 0.05)." (PMID 41495871, 2026). "The research suggests that Klotho functions by modulating several cellular signaling pathways, contributing to reduced cell growth and increased programmed cell death of cancer cells." (PMID 40004457, 2025).
cancer (continued). "In research to better understand and treat this malignancy, Klotho was found to play a role in the many physiological pathways affected by this cancer." (PMID 40004457, 2025). "The findings revealed that SOX17 upregulated Klotho gene expression in this cancer by binding to the Klotho gene promoter." (PMID 40004457, 2025). "This review details Klotho’s multifaceted contributions to cancer suppression and its potential as a therapeutic target, enhancing the understanding of its significance in cancer treatment and prognoses." (PMID 40004457, 2025). "Research on Klotho and cancer is usually conducted on animal models, followed by clinical trials involving only a limited number of patients." (PMID 39796185, 2025). "Recent research on the functions of the Klotho gene has found its close correlation with malignant tumors." (PMID 39796185, 2025). "Despite the ample literature on tissue Klotho in cancer, publications on serum Klotho and survival outcomes among cancer populations are rare." (PMID 40696614, 2025). "The inhibition of the PI3K/Akt pathway with the inhibitor LY294002 minimized the cancer promotion seen with Klotho knockdown." (PMID 40004457, 2025). "In recent times, Klotho's role in carcinogenesis, cancer development, and prognosis has garnered heightened interest." (PMID 40119098, 2025). "Klotho, initially identified as an anti-aging gene, has been shown to play significant roles in cancer biology." (PMID 40004457, 2025). "Collectively, these findings indicate that Klotho is a critical biomarker in salivary gland malignant tumors." (PMID 40427517, 2025). "Many recent studies have proven that Klotho overexpression extends patient survival in different types of cancers." (PMID 39796185, 2025). "While non-cancer individuals display an initial decline in Klotho levels at higher PIV values followed by stabilization, cancer survivors demonstrate a more pronounced and sustained decrease in Klotho levels at elevated PIV values." (PMID 40519908, 2025). "More cohort studies of specific cancer types from basic and clinical perspectives are needed to elucidate the potential role of serum Klotho." (PMID 40696614, 2025). "Animal research evidence further supports a direct relationship between Klotho expression and cancer progression, suggesting that Klotho suppression correlates with higher histologic grades (P = 0.013) and increased Ki-67 expression (P = 0.024)." (PMID 40519908, 2025). "A series of studies have indicated that epigenetic alterations of the anti-aging gene Klotho are emerging as a focus in cancer research." (PMID 40427517, 2025). "Cancer survivors exhibited significantly lower Klotho levels than non-cancer participants (813.74 ± 8.55 vs. 849.69 ± 5.08 pg/mL; P < 0.0001), as well as higher PIV values (320.07 ± 6.58 vs. 299.07 ± 3.44; P = 0.0059)." (PMID 40519908, 2025). "A study of frail individuals reported a U-shaped relationship between serum Klotho levels and cancer-related mortality, demonstrating a similar pattern of association to that found in our study, albeit in a different population." (PMID 40696614, 2025). "On the other hand, exogenous administration of Klotho or its soluble form (sKL) has shown therapeutic effects in preclinical cancer models, suggesting it should be utilized as a treatment approach." (PMID 40004457, 2025). "Cancer survivors exhibited significantly lower klotho levels (813.74 ± 8.55 vs. 849.69 ± 5.08 pg/mL, P < 0.0001) and higher PIV values (320.07 ± 6.58 vs. 299.12 ± 3.44, P = 0.0059)." (PMID 40519908, 2025). "The use of miR-199-5p mimics counteracted the metastasis inhibition induced by circ-ITCH overexpression and reduced Klotho expression in cancer." (PMID 40004457, 2025). "KL exhibits pleiotropic activity in tissues, and several studies have demonstrated its role in tumorigenesis and cancer progression, as well as cancer prognosis." (PMID 40004457, 2025).
cancer (continued). "The National Health and Nutrition Survey (NHANES) data from a large population research was used for the first time to analyze the relationship between serum Klotho and cancer." (PMID 40119098, 2025). "Among cancer survivors, Klotho levels in Q4 showed the most significant decline compared to those in Q1, with a coefficient of β = -59.13 (95% CI: -116.43, -1.83, P = 0.0478; P for trend = 0.0233)." (PMID 40519908, 2025). "This study, for the first time, established a connection between the UPR pathway and the role of Klotho in cancer." (PMID 40004457, 2025). "Conversely, we also found that pretreatment with vitamin C at a concentration of 10 μg/mL was able to restore Klotho release by these cancer cells after LPS stimulation." (PMID 38337668, 2024). "In a similar way, the protein KLOTHO is a molecule initially described as an antiaging molecule with multiple activities dysregulated in a set of diseases like cancer." (PMID 39199335, 2024). "Downregulation of KLOTHO by different epigenetic mechanisms has been reported in several types of cancer, resulting in aberrations in FGF signaling, as well as disturbed insulin-like growth factor 1 receptor (IGF-1R) and the Wnt/β-catenin signaling pathway." (PMID 39199335, 2024). "Klotho expression is reduced or silenced in several cancers, due mostly to epigenetic changes such as histone modifications, DNA hypermethylation at promoter sites and miRNAs activity, as already observed for other tumor suppressor genes." (PMID 37681914, 2023). "Cell–cell interaction analysis for K and KL demonstrated a salient interaction between cancer cells and endothelial cells." (PMID 36871040, 2023). "In cancer, Klotho proteins have been shown to interact with multiple cellular signaling pathways, enhancing or blocking carcinogenesis, as previously reviewed." (PMID 37958253, 2023). "Klotho expression is nearly completely suppressed in many cancer types and is positively correlated with a better prognosis." (PMID 37759974, 2023). "We did a stratified analysis and found some potential interactions between serum Klotho level and age, sex, race/ethnicity and BMI in klotho‐cancer correlation (p‐interactions as <0.0001, 0.0006, <0.0001, <0.0001, respectively)." (PMID 35841322, 2023). "In vitro studies provided insights into the regulation of Klotho protein’s expression and its effects on cancer cells." (PMID 37958253, 2023). "The present review aims to analyze scientific data regarding the role of Klotho proteins in cancer and to retrieve information regarding their potential use as diagnostic and prognostic biomarkers." (PMID 37958253, 2023). "Enrichment analysis targeting cancer cell clusters demonstrated that cancer cell adhesion process was also defected in KL groups, which aroused our attention to cancer cells themselves and cancer-T-cell interactions." (PMID 36871040, 2023). "αKlotho levels are epigenetically downregulated in cancer, and overexpression or treatment with soluble Klotho or the αKlotho domain slows growth of cancer cells in vitro and in vivo." (PMID 38069256, 2023). "Klotho acts as an antitumor protein, blocking cancer cell proliferation and migration by modulating different signaling pathways usually involved in cancer, such as the Wnt/β-catenin and phosphoinositide 3-kinase (PI3K)/Akt pathways." (PMID 37681914, 2023). "Overall, the datasets published between 2012 and 2022 provide evidence supporting the development of Klotho genes and their mRNA and protein products as potential prognostic markers in multiple types of cancer, especially in the prediction of patient survival." (PMID 37958253, 2023). "We confirmed the down-expression of klotho in canine mammary gland tumors, which was greater in malignant tumors than in benign tumors." (PMID 35666743, 2022). "Focusing on the relationship between klotho and cancer, research is underway to develop a cancer treatment based on klotho." (PMID 35666743, 2022).